MIR1273C (microRNA 1273c)
Synonyms: hsa-mir-1273c
Gene: MicroRNA gene on chromosome 6 (154,853,360 to 154,853,436, forward strand). Ensembl gene ENSG00000264814.
Homologues: Orthologues: chimpanzee MIR1273C (100% identical).